C7 (complement C7)
Description:
Component of the membrane attack complex (MAC), a multiprotein complex activated by the complement cascade, which inserts into a target cell membrane and forms a pore, leading to target cell membrane rupture and cell lysis. The MAC is initiated by proteolytic cleavage of C5 into complement C5b in response to the classical, alternative, lectin and GZMK complement pathways. The complement pathways consist in a cascade of proteins that leads to phagocytosis and breakdown of pathogens and signaling that strengthens the adaptive immune system. C7 serves as a membrane anchor. During MAC assembly, associates with C5b and C6 to form the C5b-7 complex, a key lipophilic precursor of the MAC complex, which associates with the outer leaflet and reduces the energy for membrane bending.
Tractability: Antibody: UniProt places it where antibodies can reach, with high confidence; its Gene Ontology location is reachable by antibodies, with high confidence; UniProt predicts a signal peptide or a membrane-spanning region.
Gene: Protein-coding gene on chromosome 5 (40,909,419 to 41,020,216, forward strand). Ensembl gene ENSG00000112936.
Subcellular location: Secreted; Target cell membrane
Pathways (Reactome):
Immune System: Regulation of Complement cascade; Terminal pathway of complement
Gene Ontology:
Molecular function: wide pore channel activity
Biological process: complement activation; complement activation, GZMK pathway; killing of cells of another organism; positive regulation of immune response; immune response; transmembrane transport
Cellular component: extracellular exosome; extracellular region; membrane attack complex; other organism cell membrane; plasma membrane
Genetic constraint (gnomAD): Loss-of-function variants: 51 observed, 69.54 expected, observed/expected ratio (o/e) 0.73, 90% interval 0.58 to 0.93. The upper end of that interval is the gene's LOEUF score, 0.93, which puts it in group 3 of 6, group 1 being the genes least tolerant of losing a copy. Missense variants: 869 observed, 835.32 expected, observed/expected ratio (o/e) 1.04, 90% interval 0.98 to 1.1. Synonymous variants: 340 observed, 303.53 expected, observed/expected ratio (o/e) 1.12, 90% interval 1.02 to 1.23.
Homologues: Orthologues: chimpanzee C7 (99% identical), macaque C7 (96% identical), pig C7 (83% identical), dog C7 (81% identical), guinea pig C7 (76% identical), rat C7 (76% identical), mouse C7 (74% identical), tropical clawed frog c7 (54% identical), zebrafish c7b (44% identical), zebrafish c7a (41% identical). Paralogues in human: C6 (33% identical), C8A (19% identical), CSMD2 (19% identical), C8B (19% identical), CSMD3 (19% identical), CSMD1 (18% identical), SVEP1 (16% identical), C9 (16% identical), CR1 (14% identical), PAPPA2 (13% identical), PAPPA (13% identical), CFH (12% identical), and 27 more.
Diseases named in the same sentence as C7 in open-access papers:
C7 is named in the same sentence as 57 diseases in open-access papers, as found by Europe PMC text mining. Sharing a sentence is not in itself a finding about the gene and the disease. The quoted sentences say what the papers report.
ovarian carcinoma (7 papers, 2006 to 2025). A malignant neoplasm originating from the surface ovarian epithelium. "Additionally, C7 was identified as a tumor suppressor in ovarian cancer and non-small-cell lung cancer." (PMID 36868311, 2023). "Complement 7 (C7) and complement factor H (CFH), both of which are components of the complement system, have previously been identified as potent indicators of complement activation in endometriosis and endometriosis-associated ovarian cancer." (PMID 36339397, 2022). "Additionally, C7 mRNA level expression showed a gradual downward trend in normal, benign, borderline, and malignant ovarian tissues, and C7 expression was negatively related to tumor grade in ovarian cancer patients." (PMID 34631552, 2021). "Furthermore, C7 mRNA expression levels show a gradual decline from normal to benign, borderline, and malignant ovarian tissues, and C7 expression is inversely correlated with tumor grade in ovarian cancer patients." (PMID 41034734, 2025).
recessive dystrophic epidermolysis bullosa (7 papers, 2014 to 2025). "Recessive dystrophic epidermolysis bullosa (RDEB) is caused by mutations in COL7A1, leading to loss or dysfunction of type‐VII collagen (C7), a protein essential for skin stability." (PMID 39853777, 2025). "Recessive Dystrophic Epidermolysis Bullosa (RDEB) is a rare inherited skin disease caused by variants in the COL7A1 gene, coding for type VII collagen (C7), an important component of anchoring fibrils in the basement membrane of the epidermis." (PMID 37161592, 2023). "Recessive dystrophic epidermolysis bullosa (RDEB) is a rare, debilitating autosomal recessive disease caused by biallelic mutations in COL7A1, the gene encoding type VII collagen (C7)." (PMID 36253825, 2022). "Recessive dystrophic epidermolysis bullosa (RDEB) is a severe genodermatosis caused by loss-of-function mutations in the COL7A1 gene, which encodes for type VII collagen (C7) protein." (PMID 37213713, 2023). "The most severe form of EB is recessive dystrophic epidermolysis bullosa (RDEB), attributed to mutations in the COL7A1 gene, that encodes the skin structural protein type VII collagen (C7)." (PMID 34884578, 2021). "Recessive dystrophic epidermolysis bullosa (RDEB) is an inherited skin fragility disorder caused by mutations in the COL7A1 gene, which encodes collagen VII (C7), an extracellular matrix (ECM) adhesion protein." (PMID 26194911, 2015).
systemic lupus erythematosus (5 papers, 2017 to 2023). An autoimmune multi-organ disease typically associated with vasculopathy and autoantibody production. "The DEGs were significantly enriched (Q ≤ 0.05) in the pathway of systemic lupus erythematosus (ID: 05322), which involved 7 DEGs including HIST1H2AL, HIST1H2BJ, HIST4H4, C1 R, C4B_2, C7, and LOC110384692." (PMID 32635817, 2020).
breast carcinoma (4 papers, 2021 to 2025). "Next, survival analysis of the Kaplan Meier-plotter database showed that breast cancer patients with a higher C7 mRNA expression had a shorter overall survival compared with those with a lower C7 mRNA expression." (PMID 34631552, 2021). "Notably, C7, MMP13, and PLAU have been reported as promoters of breast cancer progression." (PMID 41150812, 2025).
meningococcal infection (4 papers, 2012 to 2023). Infections with bacteria of the species neisseria meningitidis. "C7 deficiency contributes to susceptibility to a variety of immune and infectious diseases, such as meningococcal infection, and rare damaging variants of other complement components have been reported to be enriched in age-related macular degeneration." (PMID 31032141, 2019). "While deficiencies in the terminal complement factors such as C7 are associated with Neisseria meningitidis infections, their function in mycobacterial infections is unknown." (PMID 22973398, 2012).
atherosclerosis (3 papers, 2023 to 2025). A disease characterized by the build-up of fatty material and calcium deposition in the arterial wall resulting in partial or complete occlusion of the arterial lumen. "In particular some studies demonstrated that TREM2 is protective for atherosclerosis, while the increase of the presence of some other proteins, like SERPINA3 and C7 led to an increase of cardiac mortality and coronary artery disease respectively." (PMID 40758327, 2025).
endometriosis (3 papers, 2022 to 2025). The growth of functional endometrial tissue in anatomic sites outside the uterine body. "The difference in the results of dataset GSE7305 demonstrated that all NRDEGs were statistically significant, and the expression levels of C7, HOOK1, PKP3, AHR, GJB1, and MYO6 in different groups of endometriosis dataset GSE7305 were statistically significant (P < 0.001)." (PMID 37817158, 2023).
liver fibrosis (3 papers, 2020 to 2022). "Moreover, Complement C7 acted as a potential biomarker to identify those NASH patients with significant/advanced liver fibrosis." (PMID 31860081, 2020). "Complement component 7 (C7) was positively correlated with liver fibrosis in NASH, while complement component 8 (C8) γ chain was negatively correlated with liver fibrosis in NASH." (PMID 36569882, 2022). "The CKG automatically reproduced our previous results showing dysregulation of proteins involved in immune system regulation and inflammation, such as C7, JCHAIN, PIGR and A2M, a known marker of liver fibrosis for which CKG reported 14 publications, confirming this connection." (PMID 35102292, 2022).
non-small cell lung carcinoma (3 papers, 2016 to 2023). A group of at least three distinct histological types of lung cancer, including non-small cell squamous cell carcinoma, adenocarcinoma, and large cell carcinoma. "Proposed roles of complement C7 in ovarian and non-small cell lung cancer are inflammatory process regulation and possibly tumor suppression." (PMID 33673507, 2021).
complement deficiency (2 papers, 2021 to 2025). A genetic deficiency of any of the component of the complement system (including the classical, alternative, and terminal pathway components), that can either be acquired or inherited. "C7 deficiency is the second most frequent complement deficiency in Japan, after C9 deficiency, affecting approximately one in 10,000 individuals." (PMID 41195038, 2025).
COVID-19 (2 papers, 2023 to 2025). A disease caused by infection with severe acute respiratory syndrome coronavirus 2. "A proteomic studythat followed 113 COVID-19 patients and 39 healthy controls for upto one year showed persistent complement activation and thromboinflammation,marked by low levels of C7 complexes and high levels of C5bC6 complexes." (PMID 40997940, 2025). "Of note, we observed a localized downregulation of certain complement factors (C1QB, CFD, and C7) and interferon response genes (IFI6 and ISG15), in contrast to their enrichment in COVID-19 lungs compared to control lungs in our samples and in others analyzed in previous works." (PMID 37858234, 2023).
diabetic kidney disease (2 papers, 2025 to 2026). Progressive kidney disorder caused by vascular damage to the glomerular capillaries, in patients with diabetes mellitus. "Complement C1s are associated with insulin resistance and diabetic retinopathy, whereas complement C7 has been associated with the early stages of diabetic kidney disease." (PMID 40333882, 2025).
fibrosis (2 papers, 2020 to 2025). the formation of excess fibrous connective tissue in an organ or tissue in a reparative or reactive process. "In fibrosis, complement component 7 (C7) was elevated in advanced (≥F3) vs. mild fibrosis (<F2) (log2 fold change = 0.95, adjusted p = 0.002) and correlated with MR elastography-derived liver stiffness (R = 0.38, p = 0.004)." (PMID 41301514, 2025). "Elevated levels of Complement C7 were detected in NASH patients with significant/advanced fibrosis and were a perfect classifier for patients included in this pilot study." (PMID 31860081, 2020).
gastric cancer (2 papers, 2018 to 2022). A primary or metastatic malignant neoplasm involving the stomach. "This study aims to explore the relationship between complement component 7 (C7) polymorphisms and the risk of gastric cancer (GC)." (PMID 35111412, 2022). "Among the top 10 DRGs for Chinese (GSE54129), six genes have been reported to be gastric cancer (GC) related (REG4, ANXA13, C7, ASS1, MSMB, CREB1) and the rest four were directly regulated by known gastric cancer genes in our GRNs, in which two genes are also cancer related (BPTF, CLCA1)." (PMID 29745833, 2018).
hepatocellular carcinoma (2 papers, 2021 to 2025). A malignant tumor that arises from hepatocytes. "In hepatocellular carcinoma, complement C7 was highly expressed in the cancer cells, where the role was demonstrated to be maintenance of tumor initiating cell stemness." (PMID 33673507, 2021).
prion disease (2 papers, 2019 to 2023). A transmissible disease that is caused by a protein that is able to induce abnormal folding of normal cellular proteins, leading to characteristic spongiform brain changes, which are associated with neuronal loss without an inflammatory response. "The genes C1QB, C1QC, C7, and NCAM1 were downregulated for Ca and partake in the prion disease pathway." (PMID 31481722, 2019).
prostate carcinoma (2 papers, 2023 to 2024). A carcinoma that arises from epithelial cells of the prostate gland. "The downregulation of C7 was associated with poor differentiation and subsequently a poor prognosis for certain cancers such as ovarian, gastric and prostate cancer and NSCLC." (PMID 39590310, 2024). "C7, one of the terminal complement proteins involved in the formation of the membrane-attack complex, is proposed as a prognostic marker for prostate cancer." (PMID 36845686, 2023).
viral infection (2 papers, 2021 to 2023). "The expression of viral proteins C7 and E3 was determined to verify viral infection." (PMID 37217469, 2023).
Alzheimer disease (1 paper, 2019). A progressive, neurodegenerative disease characterized by loss of function and death of nerve cells in several areas of the brain leading to loss of cognitive function such as memory and language. "Our current results indicated that C7, a canonical terminal component in the complement cascade, might be also involved in the early pathological stage of Alzheimer's disease, together with the other initial components." (PMID 31032141, 2019). "Our results strongly suggest the active roles of C7, together with other complement components such as the GWAS hits CR1, CLU and CFH, in the development of Alzheimer's disease." (PMID 31032141, 2019).
Cachexia (1 paper, 2020). Severe weight loss, wasting of muscle, loss of appetite, and general debility related to a chronic disease. "We found 71 proteins that correlated with cachexia severity via weight loss grade, weight loss, skeletal muscle index and radiodensity (r ≥ |0.50|, p ≤ 0.05), including some known cachexia mediators/markers (LEP, MSTN, ALB) as well as novel proteins (e.g., LYVE1, C7, F2)." (PMID 33334063, 2020).
cataract (1 paper, 2023). Partial or complete opacity of the crystalline lens of one or both eyes that decreases visual acuity and eventually results in blindness. "In African Americans with POAG, five complement proteins were significantly elevated in the AH samples compared to those with cataracts: C4A (FC = 2.33, p = 0.027), C4B (FC = 1.69, p = 0.015), complement component C7 (FC = 1.38, p = 0.025), F2 (FC = 1.31, p = 0.023), and C3 (FC = 1.21, p = 0.027)." (PMID 37763167, 2023).
cervical cancer (1 paper, 2024). A primary or metastatic malignant neoplasm involving the cervix. "In cervical cancer, the upregulation of C7 can suggest increased complement activation, leading to membrane attack complex (MAC) formation and the recruitment of immune cells." (PMID 39590310, 2024).
cognitive decline (1 paper, 2021). "Hence, in the current study, for the first time, we demonstrate that C7 (at protein level) and ZYX (in human sample) might be novel neuron-derived protein markers for cognitive decline." (PMID 34512304, 2021).
glaucoma (1 paper, 2017). Increased pressure in the eyeball due to obstruction of the outflow of aqueous humor. "We quantified the majority of key proteins associated with classical complement pathway, such as C1q, C1s, C1r, C4a, C4b, C3, C5, C6, C7, C8a, C8b, C8g and C9, as up-regulated in glaucoma condition for both vitreous and retinal tissues when compared to the controls." (PMID 28978942, 2017).
hyperopia (1 paper, 2017). A refractive error in which rays of light entering the eye parallel to the optic axis are brought to a focus behind the retina, as a result of the eyeball being too short from front to back. "A diverse range of complement-related genes were differentially-expressed, with components and regulators of both the classical and alternate pathways up-regulated in late myopia (CS1, PROS1, C1QB and CFD) and late hyperopia (SERPING1, C1QA, CRP, C7 and CFD)." (PMID 28852117, 2017).
neuroblastoma (1 paper, 2021). Neuroblastoma (NB) is the most common solid, extracranial childhood tumor. "In summary, transcriptomic expression of the C7 gene was previously identified as a risk factor for AD, whereas ZYX was known to be degraded by Aβ peptides in the neuroblastoma cell model." (PMID 34512304, 2021).
preeclampsia (1 paper, 2021). Preeclampsia is a hypertensive disorder of pregnancy that is characterized by new-onset hypertension with proteinuria presenting after 20 weeks of gestation, and depending on mild or severe forms may initially present with severe headache, visual disturbances, and hyperreflexia. "Additionally, complement-associated genes were reduced in early-onset preeclampsia compared to healthy placentas (P=0.007), including complement 7 (C7), complement C1q A chain (C1QA), complement 2 (C2), and complement C1r (C1R)." (PMID 34992598, 2021). "The present study confirmed that C7 is a potential gene candidate to discriminate early-onset from late-onset preeclampsia, and suggests a generally compromised complement system in early-onset preeclampsia placentas." (PMID 34992598, 2021).
prostate tumours (1 paper, 2020). "Reduced C7 mRNA (p = 0.0244) and CFD and C7 protein expression was validated in murine prostate tumours." (PMID 31740786, 2020).
vasculitis (1 paper, 2013). "The low mRNA level of C7 measured in DBA/2 mice suggests that downstream regulation of the complement system is not important in the induction of vasculitis in the aortas or coronary arteries of DBA/2 mice." (PMID 24063402, 2013).